SIRT2 (sirtuin 2)
Diseases named in the same sentence as SIRT2 in open-access papers (continued):
Sharing a sentence is not in itself a finding about the gene and the disease.
depression (continued). "SIRT2 alteration has been reported in mood disorders; however, the role of SIRT2 in depression remains unclear." (PMID 25672834, 2015). "Despite the data indicating an association between SIRT2 and neurodegenerative disorders, there is no direct evidence that SIRT2 protein levels in the hippocampus can actually affect behaviors associated with depression." (PMID 25672834, 2015). "Furthermore, inhibiting SIRT2 by tenovin-D3 resulted in depression-like behaviors and impaired hippocampal neurogenesis in rats." (PMID 25672834, 2015). "Since SIRT2 overexpression in the hippocampus has an antidepressant-like effect, we asked whether SIRT2 inhibition produces depression-related behaviors." (PMID 25672834, 2015). "However, what has yet to be further elucidated is whether the anti-inflammatory effects contribute to the SIRT1 and SIRT2 modulators’ protection in the depression models and other mechanisms involved in symptoms or disorders." (PMID 33669121, 2021). "It was also indicated that the SIRT2 T/T genotype might exert protection against depression." (PMID 33669121, 2021). "Therefore, we aimed to determine whether SIRT2 can restore stress-induced suppression of neurogenesis in a rat chronic unpredictable stress (CUS) model of depression." (PMID 25672834, 2015). "Therefore, SIRT2 may play an important role in neurological disorders, and may represent a novel therapeutic target in the prevention of depression." (PMID 25672834, 2015). "Among their top 10 most significant proteins that were altered after treatment were the same proteins that we found in our OPLS and OPLS-DA models for depression and anxiety (CXCL6, STAMPB, CXCL1, SIRT2, AXIN1, CXCL5, ST1A1, and IL-7)." (PMID 36979692, 2023). "In this study, we have identified the expression of SIRT2 in the hippocampus; treatment with Ad-SIRT2-GFP reversed the CUS-induced a reduction of depression-like behaviors and hippocampal neurogenesis." (PMID 25672834, 2015). "Chronic unpredictable stress produces a depression-like phenotype, which is ameliorated by SIRT2 inhibition within the hippocampus but not the prefrontal cortex or dentate gyrus." (PMID 39404407, 2024). "Interestingly, R‐KET is unable to interact with SIRT2 and shows no apparent inhibition of LPS‐induced inflammation and depression‐like behaviors." (PMID 40171943, 2025).
gastric cancer (14 papers, 2014 to 2025). A primary or metastatic malignant neoplasm involving the stomach. "For instance, SIRT2 activates the RAS/ERK/JNK/MMP-9 pathway in gastric cancer to raise PEPCK1 protein levels, mitochondrial activity, and cell migration and invasion." (PMID 39479446, 2024). "SIRT2 can play a pro-cancer role in gastric cancer, but can act as a protective factor in colorectal and cervical cancers." (PMID 37723477, 2023). "In gastric cancer, SIRT2 had been found to be upregulated compared to adjacent normal tissues and also correlated with poor patient survival." (PMID 33014852, 2020). "In the GSE63089 dataset, we observed increased SIRT2 expression for gastric cancer tissues than paired normal tissues (p = 0.001)." (PMID 28061480, 2017). "Importantly, this result is consistent with SIRT2 inhibition reducing the migratory and invasive capacity of gastric cancer and osteosarcoma cells in Transwell assays both with and without Matrigel." (PMID 39682770, 2024). "Given that gastric tumors (especially malignant tumor types) have higher copper and lactate concentrations than normal tissues, combined treatment with copper ionophore– elesclomol and SIRT2-specific inhibitors to trigger cuproptosis obviously improves the efficacy of gastric cancer treatment." (PMID 37863889, 2023). "Overall, this study elucidates the molecular mechanism of LINC00152 underlying the malignant phenotype of GC cells by mediating miR-138/SIRT2 axis, which provides a new understanding of the role and molecular mechanism of lncRNA in GC and also provides a new way for the treatment of gastric cancer." (PMID 34697541, 2021). "Also, xenograft of SIRT2 knockdown gastric cancer cells in mice formed less metastatic tumors and showed slower growth than that of SIRT2 wild type cells." (PMID 34650436, 2021). "In addition, through analysis of gastric cancer patients from the TCGA dataset, we identified SIRT2 as an independent prognostic factor in gastric cancer patients." (PMID 28061480, 2017). "Based on the two GEO cohorts of patients with gastric cancer, SIRT2 mRNA expression could either be increased or decreased in tumor tissues compared with normal gastric mucosa." (PMID 28061480, 2017). "However, we surprisingly observed that expression of SIRT2 was significantly downregulated in gastric cancer tissues in patients from GSE29272." (PMID 28061480, 2017). "Given that gastric tumors (especially malignant tumor types) have higher copper and lactate concentrations than normal tissues, treatment with copper ionophores to bind copper ions and SIRT2-specific inhibitor may serve as a feasible and available strategy for gastric cancer therapy." (PMID 37863889, 2023). "In gastric cancer, SIRT2, as a downstream target of miR-138, can increase PEPCK1-related metabolism, thereby promoting gastric cancer cell migration and invasion through the RAS/ERK/JNK/MMP-9 pathway." (PMID 36101744, 2022). "Mechanically, SIRT2 altered PEPCK1 activity, and mitochondrial respiration while inducing gastric cancer cell migration and invasion by activating the RAS/ERK/JNK/MMP-9 pathway." (PMID 33014852, 2020). "All gastric cancer cell lines except for NUGC-4 and STKM-1 cells expressed high levels of SIRT1 protein, and SIRT2 expression levels were low in all cell lines except for MKN-45 cells." (PMID 25033286, 2014). "Ac-α-tubulin increased only in one cell line (MKN-45) treated with tenovin-6, hence inhibition of SIRT2 deacetylation activity could not be definitely shown in gastric cancer cells." (PMID 25033286, 2014).
colitis (13 papers, 2014 to 2025). Inflammation of the colon. "It was previously reported that Sirt2 knockout mice are slightly more susceptible to DSS-induced colitis, which is opposite to the Sirt2 inhibition phenotype." (PMID 38648480, 2024). "When colitis becomes severe and cumulative pro‐inflammatory cytokines drive Tregs to differentiate into Treg/Th17 cells, Sirt2 expression would alleviate pathogenic Treg/Th17 cell generation to thus favor the resolution of colitis." (PMID 38415949, 2024). "In these studies, SIRT2 deficiency sustained brain inflammation, colitis, and collagen-induced arthritis, but protected from renal and liver inflammation." (PMID 28894448, 2017). "SIRT2 deficiency sustained brain inflammation in a model of traumatic brain injury and increased the severity of collagen-induced arthritis and colitis." (PMID 28894448, 2017). "Age- and sex-matched Sirt2−/− and Sirt2+/+ littermate mice were subjected to dextran sulfate sodium (DSS)-induced colitis and analyzed for colitis susceptibility." (PMID 25072851, 2014). "Here we showed that SIRT2 deficiency led to a more severe colitis compared to that seen in Sirt2+/+ control mice." (PMID 25072851, 2014). "To study the possible involvement of SIRT2 in the pathogenesis of colitis, we first generated a Sirt2 deficient mouse line (Sirt2−/−) by targeting part of the SIRT2 deacetylase domain (exons 5–7), by homologous recombination in ES cells." (PMID 25072851, 2014). "Taken together these data show that SIRT2 plays an important role in protecting from DSS-induced colitis and that its deficiency exacerbates the clinical and pathological severity of disease progression." (PMID 25072851, 2014). "In a colitis model, Lo and colleagues showed that the reduction of SIRT2 could also be associated with a reduction of the M2-associated anti-inflammatory pathway." (PMID 35886959, 2022). "Sirt2 deficient mice are more sensitive to DSS-induced colitis compared to wild type littermates." (PMID 29686974, 2018). "To test whether Sirt2 deficiency contributes to the development of colitis, we exposed Sirt2+/+ and Sirt2−/− mice to DSS to chemically induce intestinal inflammation." (PMID 25072851, 2014). "To gain further insight into the molecular mechanisms underlying the effects of Sirt2 deletion on DSS-induced colitis, we investigated whether the effects observed in BMDMs were associated with alterations in the acetylation of NF-κB." (PMID 25072851, 2014). "The exact role of Sirt2 in colitis development presumably depends on the extent of autoimmunity and inflammation." (PMID 38415949, 2024). "It is, therefore, possible that macrophages or dendritic cells induce Sirt2 expression in Tregs in normal lamina propria whereas colitis‐related inflammatory mediators inhibit Sirt2 expression." (PMID 38415949, 2024). "In both cases, no convincing molecular mechanisms were available to explain the reported effect of Sirt2 in colitis." (PMID 38648480, 2024). "Our study here validated two seemingly conflicting reports regarding the role of Sirt2 in the DSS-induced mouse colitis model." (PMID 38648480, 2024). "Overall, our data support a model that Sirt2 inhibition provides beneficial effects in the DSS-induced colitis model with a substrate-dependent mechanism." (PMID 38648480, 2024). "By inhibiting Sirt2, the endocytosis of E-cadherin is inhibited, leading to an improved epithelium barrier and protection of mice in the colitis model." (PMID 38648480, 2024). "Both reports concern the effects of Sirt2 in the dextran sodium sulfate (DSS)-induced colitis model in mice." (PMID 38648480, 2024). "Future investigations using inducible Treg‐specific and Treg/Th17‐specific Sirt2 knockout or knock‐in models will provide insights into the significance of Sirt2 in colitis." (PMID 38415949, 2024). "In the present study, we demonstrate that SIRT2 is critical for modulating macrophage polarization and intestinal permeability, thereby inhibiting the development of colitis." (PMID 25072851, 2014).
colitis (continued). "In the present study, we identified a novel role for SIRT2 as a potential suppressor of DSS-induced colitis in the mouse." (PMID 25072851, 2014). "Since colitis is a systemic inflammatory disease, we measured cytokine levels in the plasma of Sirt2+/+ and Sirt2−/− mice, during basal conditions and after DSS treatment." (PMID 25072851, 2014). "More specifically, SIRT2 knockout (Sirt2−/−) mice developed more severe colitis when exposed to the chemical colitis inducer, dextran sulfate sodium (DSS)." (PMID 25072851, 2014). "We therefore hypothesized that Sirt2 is involved in colitis by regulating Arf6 fatty-acylation and activation, thus influencing the integrity of intestinal epithelium." (PMID 38648480, 2024). "We next sought to understand the mechanism via which Sirt2 affects DSS-induced colitis." (PMID 38648480, 2024). "We were curious to find out whether Sirt2 inhibition/deletion offers protection in DSS-induced colitis and attempted to validate the literature experiments and further investigate the molecular mechanism for the role of Sirt2 in DSS-induced colitis." (PMID 38648480, 2024). "Sirt2, therefore, could either exacerbate or improve colitis progression, depending on the delicate balance among Tregs and Treg/Th17 cells (and even Th17 cells)." (PMID 38415949, 2024). "In the early stage of colitis when bowel inflammation is mild, Sirt2 expression could undermine Treg function and thus should be inhibited." (PMID 38415949, 2024). "In this regard, Sirt2 would prevent Treg/Th17 cell generation to curb colitis." (PMID 38415949, 2024). "Importantly, in DSS-induced colitis mice, Sirt2 inhibitor treatment also reduced mouse gut permeability to FITC-dextran." (PMID 38648480, 2024). "In one report, Sirt2 knockout mice performed worse than wild-type mice in DSS-induced colitis." (PMID 38648480, 2024). "Furthermore, given that similar effects were observed with a very different inhibitor, AGK2, we can rule out that the protective effect is due to off-target effect and conclude that Sirt2 inhibition protected mice in DSS-induced colitis." (PMID 38648480, 2024). "Thus, we were able to replicate the previous report that Sirt2 inhibitor TM protects mice in the DSS-induced colitis model." (PMID 38648480, 2024). "The ultimate effect of Sirt2 on colitis might depend on the balance among Tregs, Treg/Th17 cells, and Th17 cells." (PMID 38415949, 2024). "Furthermore, that study observed a greater proportion of activated CD4+CD69+ T cells in the mesenteric lymph nodes of Sirt2−/− mice in response to DSS-induced colitis, suggesting a role for Sirt2 in limiting CD4+ TEFF cell functions." (PMID 35296782, 2022). "However, SIRT2 has been identified as a potential suppressor of colitis through its deacetylase activity on NF-κB within bone marrow-derived macrophages in a mouse model." (PMID 31354630, 2019). "Thus, DSS resulted in a heavily exacerbated form of colitis in the Sirt2−/− mice when compared to the Sirt2+/+ animals." (PMID 25072851, 2014). "Our results demonstrate a potential role for SIRT2 as a suppressor of colitis in the mouse." (PMID 25072851, 2014). "Similarly, SIRT2 deficiency enhances the progression of NAFLD by altering gut microbiota composition and inducing metabolic disorders, whereas inhibiting SIRT2 may improve gut barrier integrity and protect against colitis." (PMID 40136715, 2025). "Therefore, if our hypothesis above is correct, we expect that TM-P4-Thal would have similar effect as Sirt2 knockout in mice in the DSS-induced colitis model." (PMID 38648480, 2024). "Notably, Sirt2 seems to inhibit both Treg function and Treg/Th17 cell generation, implying that Sirt2 could be a double‐edged sword in the context of colitis." (PMID 38415949, 2024). "And whether Sirt2 silencing influences colitis progression is unclear." (PMID 38415949, 2024). "To explore the effects of Sirt2 inhibitors in the colitis mouse model, we administered 8 to 12-wk C57BL/6 mice with 2.5% DSS to induce colitis." (PMID 38648480, 2024).
colitis (continued). "To validate this report, we administrated 8 to 12-wk Sirt2+/+ and Sirt2−/− age-matched and littermate mice with 2.5% DSS to induce colitis." (PMID 38648480, 2024). "Thus, therapies targeting SIRT2 on macrophages could be explored to treat colitis." (PMID 34671359, 2021). "In contrast, Sirt2 knockout would affect all its substrate proteins, providing a possible explanation for the different effect of Sirt2 knockout from that of Sirt2 inhibition in the DSS-induced colitis model." (PMID 38648480, 2024). "However, in the other report, a Sirt2-specific small-molecule inhibitor, TM, protected mice in DSS-induced colitis." (PMID 38648480, 2024). "We confirmed that Sirt2 genetic knockout does not provide protection, while small-molecule inhibitors of Sirt2 offer clear protection in the DSS colitis model." (PMID 38648480, 2024). "Unlike Sirt2 inhibitors, Sirt2 knockout did not offer protection in mice with DSS-induced colitis, as evidenced by the similar colon lengths, body weights, and survival rates in Sirt2+/+ and Sirt2−/− mice." (PMID 38648480, 2024). "In vivo studies showed that mice lacking SIRT2 displayed enhanced pro-inflammatory responses in a model of colitis induced by dextran sulfate sodium (DSS) as compared to wild-type mice." (PMID 34671359, 2021). "In addition to establishing that Sirt2 inhibition and knockout produce different phenotypes, our work also provides an interesting molecular mechanism for how Sirt2 disruption protects mice in the DSS-induced colitis model." (PMID 38648480, 2024). "Considering that SIRT2 deficiency does not alter the homeostasis of the intestinal epithelium under normal conditions, we hypothesized that the contribution of the immune cell compartment may be the primary event causing more severe DSS-induced colitis in the Sirt2−/− animals." (PMID 25072851, 2014). "Although Sirt2−/− mice were indistinguishable from Sirt2+/+ mice, with respect to body weight and intestinal morphology, upon a DSS challenge they developed more severe colitis." (PMID 25072851, 2014).